HNF1A (HNF1 homeobox A)
Diseases named in the same sentence as HNF1A in open-access papers (continued):
Sharing a sentence is not in itself a finding about the gene and the disease.
diabetes (continued). "The molecular basis of HNF1A abnormality in insulin secretion in human beta cells and the pathophysiological role of HNF1A in the liver, kidneys, and gut in diabetes requires further investigation." (PMID 35328643, 2022). "Three genes from the collapsing analysis were associated with increased odds of diabetes and have been reported previously: GCK, GIGYF1, and HNF1A." (PMID 36383675, 2022). "Despite the frequency of MODY3 and the association of HNF1A SNPs with T2DM, the molecular basis of HNF1A mutations leading to diabetes remains elusive." (PMID 35328643, 2022). "We also diagnosed family members with HNF1A-MODY before they started to show any symptoms of diabetes, some of them still being in early childhood." (PMID 34440499, 2021). "The HNF family of TFs is implicated in mature onset diabetes of the young (MODY), and mutations in the HNF4α, HNF1α, and HNF1β genes cause MODY, a form of non-insulin-dependent diabetes mellitus." (PMID 34771521, 2021). "We identified associations for variants in GCK, HNF1A and PDX1, which are known to be involved in Mendelian forms of diabetes." (PMID 34732801, 2021). "We herein report the cosegregation phenotypes of HCA and diabetes in two unrelated Chinese MODY 3 families with germline and somatic HNF1A mutations, and reviewed the literature concerning phenotypes of MODY 3 and HCA." (PMID 31754975, 2020). "Further, we screened eight relatives in the two independent families for diabetes, HCA and HNF1A variants." (PMID 31754975, 2020). "Accuracy of hsCRP alone was 80% when discriminating HNF1A-MODY from type 2 diabetes and 75% when comparing HNF1A-MODY with all other types of diabetes." (PMID 32528556, 2020). "Of note, several Maturity Diabetes of the Youth (MODY) and T2D associated genes such as HNF-1α, GCK, and TCF7L2 have splicing variants." (PMID 33088281, 2020). "Large-scale multi-ethnic genetic sequencing studies have challenged our understanding of the relationship between coding variants in Mendelian disease genes, including those involved in monogenic forms of diabetes such as HNF1A (MIM: 142410)." (PMID 32910913, 2020). "HNF1α is a transcription factor involved in several metabolic pathways in hepatocytes and is mutated in type 2 diabetes MODY 3 (Maturity Onset Diabetes of the Young 3)." (PMID 32784704, 2020). "We report a UK-based economic evaluation of these realistic strategies to identify individuals with monogenic diabetes (defined here as mutations in GCK, HNF1A or HNF4A genes)." (PMID 32193268, 2020). "Researchers demonstrated that elevated HNF-1α expression and binding activity in the solute carrier family 5-member 2 promoter leads to the diabetes-induced overexpression of SGLT2." (PMID 33187206, 2020). "Patients in the GCK (n = 7) and HNF1A (n = 27) groups had similar age at onset (16.1 ± 7.8 vs 20.8 ± 9.0 years; p = 0.286), diabetes duration (9.88.8 vs 15.4 ± 10.1 years; p = 0.82) or BMI (20.6 ± 4.0 vs 23.3 ± 2.8; p = 0.143)." (PMID 31576961, 2020). "While TCF7L2 isoforms are not significantly altered in T2D, both HNF-1α and GCK diabetes associated alleles result in alternative splicing variation, and isoforms of HNF-1α are associated with differential efficiency in insulin gene regulation." (PMID 33088281, 2020). "Pubmed was searched for publications on the subject by employing search terms: MODY, Maturity Onset Diabetes of the Young, monogenic diabetes, HNF1A, HNF-1 alpha, GCK, glucokinase, HNF1B, HNF-1 beta, HNF4A, HNF-4 alpha, biomarkers." (PMID 32528556, 2020). "The PCS also highlighted several other highly scoring candidates with known causal roles in relation to diabetes and obesity such as MC4R (PCS = 0.43), WFS1 (0.41), ABCC8 (0.37), LEP (0.27), GCK (0.24) and HNF1A (0.23)." (PMID 30914061, 2019). "This case-control study showed that the HNF1A gene p.I27L SNP was modestly associated with having early-onset, MODY-like diabetes in the Turkish population." (PMID 31109344, 2019).
diabetes (continued). "We report a genetic modifier of the HNF1A gene age at diagnosis that shows an effect of genetic variation on diabetes phenotype." (PMID 31109344, 2019). "The HNF1A variant p.I27L was associated with having early-onset, MODY-like diabetes in the Turkish population." (PMID 31109344, 2019). "HNF1α is a liver-enriched transcription factor involved in glucose and lipid metabolism and its mutation can lead to MODY3 subtype of diabetes." (PMID 31551932, 2019). "In keeping with previous studies, class 4–5 variants of GCK, HNF1A, and HNF4A accounted for the large majority (87%) of monogenic diabetes diagnoses." (PMID 31291970, 2019). "Women with HNF1A mutation are diagnosed as having monogenic form of diabetes type 3 (MODY3), and these women usually present with GDM, and diabetes persisting after delivery." (PMID 31114636, 2019). "For example, HNF-1α knockout mice are characteristically described as the phenotypes of both Laron-type dwarfism and non-insulin-dependent diabetes mellitus (NIDDM)." (PMID 31685031, 2019). "The aim of this study was to obtain the effects of HNF1A gene SNPs on developing MODY-like diabetes." (PMID 31109344, 2019). "At least two of them are clearly pathogenic alterations responsible for monogenic diabetes: p.Gly32Ser in the INS gene and p.Val264fs in the HNF1A gene." (PMID 31365591, 2019). "The HNF1A gene p.I27L SNP was modestly associated with having early-onset, MODY-like diabetes in the Turkish population." (PMID 31109344, 2019). "This is the first study to investigate the association between HNF1A-gene single-nucleotide polymorphisms (SNPs) and having early-onset, MODY-like diabetes mellitus in the Turkish population." (PMID 31109344, 2019). "A shorter duration of diabetes, lower HbA1c level and lower BMI at genetic diagnosis predicted successful treatment with sulfonylurea/diet alone in participants with HNF1A/HNF4A-MODY, supporting the need for early genetic diagnosis and treatment change." (PMID 30229274, 2018). "Improvement in glycaemic control among individuals with HNF1A/HNF4A-MODY is needed to prevent diabetes complications." (PMID 30229274, 2018). "The PTVs and the protein variant p.P379R were previously reported in subjects with HNF1A-MODY, while the protein variant p.A251T was identified previously in a patient with SU-sensitive diabetes." (PMID 29666556, 2018). "Within the Norwegian HUNT2 study of 1972 subjects with diabetes, a minimum prevalence of HNF1A-MODY of 0.4% was calculated, corresponding to 63 cases per million." (PMID 29666556, 2018). "Our study suggests that successful treatment with diet/sulfonylurea alone was most likely in those with HNF1A/HNF4A-MODY who had a shorter duration of diabetes, healthy BMI and lower HbA1c at the time of genetic diagnosis." (PMID 30229274, 2018). "Individuals with HNF1A/HNF4A-MODY are at increased, or at least the same, risk of developing diabetes-related complications compared with those with other diabetes subtypes." (PMID 30229274, 2018). "Individuals with HNF1A-MODY similarly to other patients with diabetes can present with typical hyperglycaemia-related symptoms as polyuria, polydipsia and weight loss." (PMID 30013516, 2018). "We also assessed the combined effect of diabetes duration and HbA1c at genetic diagnosis on the ability to achieve good glycaemic control with diet/sulfonylurea alone in individuals with HNF1A/HNF4A-MODY." (PMID 30229274, 2018). "Using this generally accepted cut off for diabetes onset we would miss more than three quarters of the HNF1A-MODY subjects identified in our study." (PMID 29666556, 2018). "It is well known that HNF1A variant-induced diabetes (HNF1A-DM) is the most common form of MODY." (PMID 30155490, 2018). "Glucokinase-maturity-onset diabetes of the young (GCK-MODY), also known as MODY type 2, is the most common type of the monogenic diabetes in Poland, and, along with a HNF1A- MODY, is one of the most common in the world." (PMID 28663157, 2017).
diabetes (continued). "HNF1A plays an important part in the pathogenesis of various diseases particularly diabetes and cardiovascular diseases." (PMID 29066969, 2017). "Among individuals with young onset and adult onset diabetes, 40 individuals (1.8% of subjects with early onset diabetes and 0.6% with late onset) were carriers of known pathogenic missense mutations in the GCK, HNF1A, HNF4A, HNF1B, ABCC8, and INS genes." (PMID 29207974, 2017). "Seven such mutations were observed in MODY genes in which heterozygous loss-of-function variants are known to be pathogenic for diabetes – three each in the GCK and HNF1A genes and one in the HNF1B gene." (PMID 29207974, 2017). "Bi-DOCS were associated with genes related to pancreas development and beta-cell function, including transcription factors mutated in monogenic diabetes (PDX1, NKX2-2, HNF1A; FDR < 0.05)." (PMID 29107594, 2017). "As for the genetic susceptibility for diabetes, ABCC8/KCNJ11 is associated with neonatal diabetes, GATA6 is associated with pancreas agenesis, and HNF1A is associated with monogenic diabetes." (PMID 28744848, 2017). "A total of 40 individuals with diabetes (1.8% of early onset sub-group and 0.6% of adult onset sub-group) were carriers of known pathogenic missense variants in the GCK, HNF1A, HNF4A, ABCC8, and INS genes." (PMID 29207974, 2017). "We then consider the three common subtypes of sulfonylurea‐treated monogenic diabetes, HNF1A and HNF4A MODY and KCNJ11/ABCC8 permanent neonatal diabetes." (PMID 28556992, 2017). "When overlaying this network with canonical pathways in NASH, HNF4A and HNF1A are connected to hepatic cholestasis, diabetes and FXR/RXR activation." (PMID 29216278, 2017). "Of these, 36 probands were seen in the adult diabetes clinic, and were tested for one or more of the monogenic diabetes genes GCK, HNF1A, HNF4A and HNF1B or the mitochondrial m.3243A>G mutation." (PMID 27330718, 2016). "Of the eight probands and five relatives with diabetes seen in our center diagnosed with HNF1A or HNF4A diabetes, three were prescribed a sulphonylurea drug at the time of molecular testing." (PMID 27330718, 2016). "The objective of our study was to identify miRNAs under the transcriptional control of HNF1β or HNF1α and assess the potential of such miRNAs as biomarkers of monogenic diabetes." (PMID 27059371, 2016). "T2DM and HNF1A-MODY groups in comparison with control group share some between-group differences but the study also revealed some type of diabetes-related differences." (PMID 27807544, 2016). "The aim of the investigation was to compare the qualitative parameters of the colonic flora in patients with HNF1A-MODY diabetes, matched controls, and patients with T2DM in a single stool sample." (PMID 27807544, 2016). "HNF1A-MODY is a monogenic form of diabetes and therefore an ideal model for the study of the beta-cell." (PMID 26110317, 2015). "In summary, plasma ghrelin level seems to depend on the etiology of diabetes and is higher in HNF1A–MODY and GCK–MODY than in both common polygenic forms of diabetes." (PMID 25987348, 2015). "Our cohort included 46 diabetic HNF1A gene mutation carriers, 55 type 2 diabetes (T2DM) subjects, 42 type 1 diabetes (T1DM) patients, and 31 glucokinase (GCK) gene mutation carriers with diabetes as well as 51 healthy controls." (PMID 25987348, 2015). "On the other hand, it was higher in HNF1A–MODY patients (as well as GCK–MODY individuals) than in both common forms of diabetes." (PMID 25987348, 2015). "Taking this into consideration, the aim of this study was to generate and evaluate differentiation potential of iPSCs from lepdb/db (db/db) mice, the model of diabetes type 2 as well as from patients with Maturity Onset Diabetes of the Young 3 (HNF1A MODY)." (PMID 25716801, 2015). "From these GWAS we already learned that several genes, such as IL6R, APOC1, GCKR and HNF1A, are associated both with systemic inflammation and cardiometabolic phenotypes such as CAD, lipids and diabetes." (PMID 25768928, 2015).
diabetes (continued). "Absolute levels of miR-224 and miR-103 were determined in the urine of n = 144 individuals including carriers of a HNF1A mutation, participants with type 1 diabetes mellitus (T1DM), type 2 diabetes mellitus (T2DM) and normal controls." (PMID 26110317, 2015). "This defect predates the clinical manifestation of diabetes as demonstrated by research in the carriers of HNF1A-MODY who were normoglycaemic and likewise in islet antibody positive relatives of those with T1DM." (PMID 26110317, 2015). "We aimed to assess the circulating ghrelin levels in HNF1A–MODY and in other types of diabetes and to evaluate its association with HNF1A mutation status." (PMID 25987348, 2015). "We have induced severe diabetes in pigs carrying a dominant-negative mutant hepatocyte nuclear factor 1-alpha (HNF1α) P291fsinsC, a maturity-onset diabetes of the young type-3 (MODY3) gene in humans." (PMID 24647409, 2014). "This is comparable with other biochemical biomarkers used in the discrimination of HNF1A-MODY from other diabetes (e.g. hs-CRP (high sensitivity C-reactive protein) and 1,5Ag (serum 1,5 anhydroglucitol)) which both have ROC AUC ∼0.8." (PMID 23799006, 2013). "Of the 37 HNF1A-MODY carriers with diabetes, 9 subjects (24.3%) had diabetic retinopathy, with proliferative retinopathy in one subject (2.7%)." (PMID 24069322, 2013). "There is somewhat limited data available on the prevalence of macrovascular disease in HNF1A-MODY carriers with diabetes." (PMID 24069322, 2013). "The strategy called genome-wide linkage study with subsequent positional cloning which led to the identification of the HNF4A and HNF1A genes, which were found to be responsible for 2 forms of monogenic diabetes, initially called MODY1 and MODY3, respectively." (PMID 22996131, 2012). "HNF1A-MODY subjects with pre-diabetes have defective glucose-induced beta cell insulin secretion indicative of reduced beta cell mass." (PMID 22808921, 2012). "This study reported on a mutation identification rate of 30.5% among Irish adults clinically selected for HNF1A-MODY from attendees at the diabetes clinic." (PMID 22808921, 2012). "Linear regression modelling in the HNF1A-MODY and T2D cases from the extended dataset showed that (young) age of onset of diabetes was the most important predictor of HNF1A-MODY (P<0.001), with urinary glucose/Cr ratio having a more modest effect (p = 0.03)." (PMID 22859960, 2012). "Mutations in HNF1A and HNF4A (encoding for hepatocyte nuclear factor 1α and 4α) are responsible for the most common form of monogenic diabetes." (PMID 20523905, 2010). "Type 2 diabetes mellitus (T2DM) is a genetically heterogeneous disease, hepatocyte nuclear factor-1 homeobox A (HNF1A) single-nucleotide polymorphisms (SNPs) playing a minor role in its pathogenesis." (PMID 19490620, 2009). "Interaction of HNF1A with lipid hepatic metabolism in diabetes has been object of relatively little study, and mostly in MODY individuals." (PMID 19490620, 2009). "The mouse phenotype described here, characterized by a low level of insulin secretion and a high level of glucosuria, is reminiscent of a monogenic (HNF1α) form of diabetes." (PMID 18074013, 2007). "The early-onset T2DM cohort included patients with monogenic diabetes resulting from mutations in the HNF1β, HNF4A, and HNF1A genes associated with Lp(a) expression, which may help explain the lower levels of Lp(a)." (PMID 40370778, 2025). "This enrichment was lower than observed in T2D cases and independent of parental diabetes history and after removing variants in HNF1A, HNF4A or HNF1B genes from the PGS (0.4 s.d." (PMID 40925988, 2025). "Mutations in HNF1A, HNF4A, and HNF1β genes involved in Lp(a) expression account for more than 50% of monogenic diabetes with a known genetic cause, which may lead to the complexity of concentrations of Lp(a) in patients with T2DM." (PMID 40370778, 2025).
diabetes (continued). "Hereditary forms of diabetes also include rare monogenic variants such as MODY (Maturity-Onset Diabetes of the Young), which follows an autosomal dominant inheritance pattern caused by specific mutations in genes such as HNF4A, GCK, HNF1A, HNF1B, PDX1, and NEUROD1." (PMID 40647303, 2025). "The heritability estimate remained consistent across multiple approaches, including restricting to HNF1A-related monogenic diabetes, phenotype correlation–genotype correlation regression and applying GREML estimation in linkage-disequilibrium adjusted kinships (LDAK)." (PMID 40925988, 2025). "HNF1A-MD patients had longer time from the diagnosis of diabetes (8.0 vs 3.5 years, p=0.046)." (PMID 41409604, 2025). "Interestingly, the phenotype is shared with certain HNF4A (MODY1) and HNF1A (MODY4) mutations that cause hyperinsulinaemia at birth before evolving to decreased insulin secretion and diabetes in later life." (PMID 38366195, 2024). "DPP4i are an option in the augmentative treatment of HNF1A-diabetes (grade C evidence)." (PMID 39025920, 2024). "Overall, our work provides a valuable resource of HNF4A and HNF1A targets in human pancreatic and hepatic cells, with a focus on the beta cells which lie at the heart of diabetes pathophysiology, revealing potential therapeutic targets and pathways to guide future strategies for treating diabetes." (PMID 38909044, 2024). "Moreover, differently from other forms of diabetes comprising T2DM, T1DM, and HNF1A-MODY, RFX6-MODY was associated with a decreased glucose-dependent insulinotropic peptide (GIP) secretion." (PMID 39201476, 2024). "What is the optimal glucose-lowering therapy in HNF1A-diabetes and HNF4A-diabetes?" (PMID 39025920, 2024). "HNF1A, GCK, and HNF1B are the genes presenting the most variants in both level 1 and level 2 databases, indicating that most of the monogenic diabetes-associated variants have been reported in these genes, as well as most of the ones confirmed as pathogenic or likely pathogenic." (PMID 38635808, 2024). "This case reveals that HNF1A MODY (and probably other causes of monogenic diabetes) can present in sub-Saharan Africa, just like in other parts of the world, and a diagnosis of MODY can lead to significant life-changing therapeutic implications for the patient." (PMID 39420387, 2024). "GLP1RA is an option in the treatment of HNF1A-diabetes (grade C evidence)." (PMID 39025920, 2024). "HNF1A/HNF4A-MODY diabetes should be considered in a young, pregestational, obese woman with symptomatic or asymptomatic hyperglycemia without ketoacidosis and a positive family history of diabetes or a history of gestational diabetes as a potential indicator of autosomal dominant inheritance." (PMID 39902162, 2024). "With the available data, we can only provide assessment of the evidence in HNF1A-diabetes although combined cohorts suggest results may be similar in HNF4A-diabetes." (PMID 39025920, 2024). "Here we used a novel conditional mouse model that allowed the study of the post-natal development in the pancreatic islet with suboptimal levels of Hnf1a, however in the absence of the confounding effects caused by hyperglycemia and diabetes." (PMID 38825059, 2024). "Recommendation: SU should be used as first-line therapy for HNF1A-diabetes (grade C evidence)." (PMID 39025920, 2024). "Clinically, such patients usually present with diabetes like patients with HNF1A or HNF4A MODY." (PMID 39408828, 2024). "Monogenic forms of diabetes are usually named after a gene, such as HNF1A (or HNF1A-MODY) diabetes." (PMID 39902162, 2024). "We systematically analyzed evidence for precision treatments for GCK-related hyperglycemia, HNF1A-, HNF4A- and HNF1B-diabetes, and mitochondrial diabetes (MD) due to m.3243 A > G variant, 6q24-transient neonatal diabetes mellitus (TND) and SLC19A2-diabetes." (PMID 39025920, 2024).